ALPK3 (alpha kinase 3)
Diseases named in the same sentence as ALPK3 in open-access papers (continued):
Sharing a sentence is not in itself a finding about the gene and the disease.
chronic lymphocytic (1 paper, 2025). "Dilated transformation in patients with ALPK3 and LAMP2 variants occurred against a background of histologically verified (Dallas criteria) chronic lymphocytic, virus-negative myocarditis (per endomyocardial biopsy or explanted heart specimens)." (PMID 41440877, 2025).
developmental delay (1 paper, 2024). "The studies published to date show a vast spectrum of extracardiac alterations in patients with ALPK3 variants, including various dysmorphic craniofacial features, skeletal abnormalities, joint contractures, myopathic features, and developmental delay, including speech delay." (PMID 39062799, 2024). "The phenotype of the proband’s daughter was even more confusing, since her facial features and developmental delay partially fitted the disorders described in biallelic ALPK3, but cascade genetic screening was negative." (PMID 39062799, 2024).
embryonic carcinoma (1 paper, 2020). "The overexpression of ALPK3 enhances differentiation of murine embryonic carcinoma cells into cardiomyocytes." (PMID 32143402, 2020).
infarction (1 paper, 2025). A localised pathological necrosis of tissue resulting from obstruction of the blood supply usually by a thrombus, an embolus, or vascular torsion. "Furthermore, the increase in remodeling-related proteins, including EPHA4, PODN, and ALPK3, pointed to favorable structural adaptation following infarction." (PMID 41373456, 2025).
liver cancer (1 paper, 2025). An epithelial or non-epithelial malignant neoplasm that arises from the liver. "Our study revealed elevated ALPK3 expression in liver cancer tissues, correlating with poor prognosis in HCC patients." (PMID 40269756, 2025).
myocarditis (1 paper, 2025). Myocarditis is a condition that is characterized by inflammation of the heart muscle (myocardium). "Taking into account the histological signs of myocarditis in the ALPK3 patient as well, this mechanism can be suggested as an important factor triggering malignant remodeling." (PMID 41440877, 2025).
polycystic kidney disease (1 paper, 2024). A usually autosomal dominant and less frequently autosomal recessive genetic disorder characterized by the presence of numerous cysts in the kidneys leading to end-stage renal failure. "Although one of the previously reported patients was described as “presenting at age 24 with renal disease”, and one more case describes a heterozygous ALPK3 carrier with independently inherited polycystic kidney disease, it did not seem to be a convincing genotype–phenotype correlation." (PMID 39062799, 2024).
renal carcinoma (1 paper, 2025). A carcinoma arising from the epithelium of the renal parenchyma or the renal pelvis. "Least supported in literature is the relatively uncharacterized ALPK3, with only its paralog, ALPK2, indicated as a tumor promotor in renal cancer." (PMID 41188181, 2025).
Skeletal myopathy (1 paper, 2024). "Interestingly, a previous study found that 20% of the ALPK3 PTV carriers had a subclinical increase in serum creatine kinases which is a feature associated with skeletal myopathy." (PMID 39036505, 2024).
sudden cardiac arrest (1 paper, 2023). Unexpected rapid natural death due to cardiovascular collapse within one hour of initial symptoms. "We described a young patient with ALPK3-associated HCM who experienced sudden cardiac arrest." (PMID 37396576, 2023).
cancer (5 papers, 2015 to 2025). A tumor composed of atypical neoplastic, often pleomorphic cells that invade other tissues. "Predicted HFI SNVs were not distributed evenly across disease subsets; SNVs in ULK4, BMP2K, PALB2, ALPK3 were more frequent in triple negative cancers (TNBC) whereas SNVs in EPHA2 was more common in ER positive cancers." (PMID 26420498, 2015).
cardiac disease (4 papers, 2019 to 2024). "In addition, in patients with benign variants and patients without identified variants, testing a wider range of cardiac disease-related genes (such as FLNC, ALPK3, CDH, etc.)not included in our study would lead to greater utility of molecular analysis." (PMID 38254962, 2024).
tumor (3 papers, 2023 to 2025). "Finally, the peptide list suggested the presence of increased Kinectin 1, Coronin 1, and ALPK3 expression in both tumor types (HCC and iCCA)." (PMID 37046807, 2023). "Protein level of tumor promoting genes (GPRASP1, APLP1, ALPK3, SPTBN5, PCDHB14, LZTS3, RGL2) were higher in tumor tissues." (PMID 37237274, 2023). "We found that most genes with hazard ratio > 1 (GPRASP1, APLP1, ALPK3, SPTBN5, PCDHB14, LZTS3 and RGL2) have a higher expression in tumor tissues than normal tissues except LINGO1 and LZTS1." (PMID 37237274, 2023).
muscular disorders (1 paper, 2024). "Unexpectedly, we identified eight patients with pathogenic variants in genes associated with muscular disorders, including MYH3, MYH7, ALPK3, and RYR1." (PMID 38321032, 2024).
ALPK3 also shares sentences with these, for which no sentence is quoted: atrial fibrillation (3 papers); dilatation (2); Noonan syndrome (2); Arrhythmia (1); atherosclerosis (1); attention deficit-hyperactivity disorder (1); autism spectrum disorder (1); bipolar disorder (1); congenital cardiomyopathy (1); coronary artery disease (1); endothelial dysfunction (1); Fabry disease (1); generalized anxiety disorder (1); hypertrophy (1); intrinsic cardiomyopathy (1); left ventricular noncompaction (1); lung adenocarcinoma (1); musculoskeletal disease (1); Myocardial fibrosis (1); obsessive-compulsive disorder (1); oral squamous cell carcinoma (1); renal disease (1); schizophrenia (1); scoliosis (1); speech delay (1); type 2 diabetes mellitus (1); unipolar depression (1); ventricular fibrillation (1); X-linked deafness (1).